FRS3 (fibroblast growth factor receptor substrate 3)
Description:
Adapter protein that links FGF and NGF receptors to downstream signaling pathways. Involved in the activation of MAP kinases. Down-regulates ERK2 signaling by interfering with the phosphorylation and nuclear translocation of ERK2.
Synonyms: SNT-2; FRS2beta; FRS2B; FRS2-beta; SNT2
Tractability: Antibody: its Gene Ontology location is reachable by antibodies, with high confidence. PROTAC: its protein half-life has been measured.
Gene: Protein-coding gene on chromosome 6 (41,770,174 to 41,787,570, reverse strand). Ensembl gene ENSG00000137218.
Subcellular location: Membrane
Pathways (Reactome):
Signal Transduction: Activated NTRK2 signals through FRS2 and FRS3; FRS-mediated FGFR1 signaling; FRS-mediated FGFR2 signaling; FRS-mediated FGFR3 signaling; FRS-mediated FGFR4 signaling; RAF/MAP kinase cascade; RND1 GTPase cycle; RND2 GTPase cycle
Disease: Signaling by ALK fusions and activated point mutants
Gene Ontology:
Molecular function: fibroblast growth factor receptor binding; identical protein binding; protein binding; transmembrane receptor protein tyrosine kinase adaptor activity
Biological process: fibroblast growth factor receptor signaling pathway; signal transduction
Cellular component: plasma membrane; membrane
Genetic constraint (gnomAD): Loss-of-function variants: 17 observed, 37.53 expected, observed/expected ratio (o/e) 0.45, 90% interval 0.31 to 0.68. The upper end of that interval is the gene's LOEUF score, 0.68, which puts it in group 2 of 6, group 1 being the genes least tolerant of losing a copy. Missense variants: 619 observed, 665.73 expected, observed/expected ratio (o/e) 0.93, 90% interval 0.87 to 0.99. Synonymous variants: 287 observed, 272.82 expected, observed/expected ratio (o/e) 1.05, 90% interval 0.95 to 1.16.
Homologues: Orthologues: chimpanzee FRS3 (99% identical), macaque FRS3 (99% identical), dog FRS3 (94% identical), pig FRS3 (92% identical), rabbit FRS3 (88% identical), rat Frs3 (88% identical), mouse Frs3 (86% identical), guinea pig FRS3 (85% identical), tropical clawed frog frs3 (60% identical), zebrafish frs3 (52% identical), Caenorhabditis elegans rog-1 (18% identical), Drosophila melanogaster CG13398 (16% identical), and 1 more. Paralogues in human: FRS2 (49% identical), DOK1 (13% identical), DOK3 (12% identical), DOK2 (11% identical), DOK6 (10% identical), DOK4 (9% identical), DOK5 (8% identical).
Diseases named in the same sentence as FRS3 in open-access papers:
FRS3 is named in the same sentence as 12 diseases in open-access papers, as found by Europe PMC text mining. Sharing a sentence is not in itself a finding about the gene and the disease. The quoted sentences say what the papers report.
prostate carcinoma (3 papers, 2011 to 2019). A carcinoma that arises from epithelial cells of the prostate gland. "FLT4 is a VEGF receptor that is implicated in angiogenesis while FRS3 is known to regulate prostate cancer progression." (PMID 25944692, 2015). "In prostate cancer cells we observed that FRS3 over-expression was able to induce an enhanced mitogenic phenotype in the presence of FGF stimulation." (PMID 22078327, 2011). "Synchronous knockdown of FRS2 and FRS3 with exposure to cytotoxic irradiation resulted in a significant reduction in prostate cancer cell survival compared to irradiation alone (p < 0.05)." (PMID 22078327, 2011). "A stable myc-tag FRS3 over-expressing clone in DU145 prostate cancer cell lines was first generated (DUFRS3)." (PMID 22078327, 2011). "Given this functional redundancy, we tested the therapeutic principle of dual targeting of FRS2 and FRS3 in prostate cancer." (PMID 22078327, 2011). "In this study we investigated the relative expression and functional role of FRS2 and FRS3 in prostate cancer." (PMID 22078327, 2011). "We have observed that combined silencing of FRS2 and FRS3 resulted in a significant inhibition in FGF induced ERK activation in prostate cancer cell lines." (PMID 22078327, 2011). "This implies FRS functional redundancy in prostate cancer cells and a potentially important role for FRS3 in maintaining aberrant FGF signalling." (PMID 22078327, 2011). "We therefore tested expression of FRS2 and FRS3 transcript by quantitative real time PCR in a panel of archival clinical prostate cancers using methods previously developed in our group." (PMID 22078327, 2011). "Given evidence of expression overlap in our cell lines, we tested functional overlap between FRS2 and FRS3 in prostate cancer." (PMID 22078327, 2011). "FRS2 and FRS3 exhibit functional redundancy in prostate cancer cells and dual inhibition effectively blocks intracellular signalling and the mitogenic effects of multiple FGFs." (PMID 22078327, 2011). "Here we investigated FRS2 and FRS3 as a means of disrupting global FGF signalling in prostate cancer." (PMID 22078327, 2011). "Our results suggest that both FRS2 and FRS3 are important in FGF mediated signalling in prostate cancer." (PMID 22078327, 2011). "In conclusion this is the first study to investigate FRS2 and FRS3 in prostate cancer." (PMID 22078327, 2011). "We next tested functional redundancy of FRS2 and FRS3 in prostate cancer cells." (PMID 22078327, 2011). "FRS2 and FRS3 mRNA were ubiquitously expressed in normal epithelial prostate cell lines (PNT1A/PNT2) and prostate cancer cell lines (LNCaP, DU145 and PC3)." (PMID 22078327, 2011). "There have been very few studies of FRS2 and FRS3 in clinical cancers and no reports in prostate cancer." (PMID 22078327, 2011). "FRS2 and FRS3 therefore do not appear to be altered in prostate cancer." (PMID 22078327, 2011). "FRS2 and FRS3 suppression in contrast, did not have any appreciable effect on EGF stimulation in either of our prostate cancer cell models." (PMID 22078327, 2011).
liver cancer (1 paper, 2024). An epithelial or non-epithelial malignant neoplasm that arises from the liver.
thyroid cancer (1 paper, 2011). "Conversely, in thyroid cancers FRS3 expression was unchanged but FRS2 expression was increased suggesting potential tissue specific FRS2 and FRS3 changes in tumours." (PMID 22078327, 2011).
cancer (2 papers, 2011 to 2021). A tumor composed of atypical neoplastic, often pleomorphic cells that invade other tissues. "Work in other tumour models have conversely shown differences in FRS2 and FRS3 between benign and cancers with specific down-regulation of FRS3 or FR2 over-expression." (PMID 22078327, 2011). "An important first step however is to determine the relative expression and function of FRS2 and FRS3 in a specific cancer." (PMID 22078327, 2011). "Taken together we believe that these results justify further studies to investigate FRS2 and FRS3 in FGFR binding and signalling in the prostate and define mechanisms by which FRS2 and FRS3 targeting appears to be more detrimental to cancer cells." (PMID 22078327, 2011). "Much less is known about FRS3 and in particular, its function in cancer cells." (PMID 22078327, 2011). "An important therapeutic question is if either FRS2 or FRS3 are over-expressed in cancer." (PMID 22078327, 2011). "Preliminary results of down-regulation in combination with a cytotoxic therapy however do suggest that targeting FRS2 and FRS3 may be specifically effective in cancer cells." (PMID 22078327, 2011). "We also tested if with increasing cancer grades there was any evidence of a progressive increase or decrease in expression and found no significant alterations (p = 0.23 for FRS2 and p = 0.87 for FRS3)." (PMID 22078327, 2011). "We also show that neither FRS2 nor FRS3 are apparently over-expressed in cancer and acknowledge that this does limit their attractiveness as a therapeutic target." (PMID 22078327, 2011). "Despite the lack of over-expression we did observe that FRS2 and FRS3 suppression had a significant and specific inhibitory effect in cancer cell lines whereas it had no discernible effect on PNT2 benign prostate cells which are known to express FGF receptors and respond to FGF stimulation." (PMID 22078327, 2011). "Thus while FRS2 and FRS3 may not be over-expressed in cancer, they may still conceivably be a viable target if their inhibition is selectively effective in cancer but not benign cells." (PMID 22078327, 2011). "In contrast to cancer cells, the clonogenic survival after radiation between scramble and siRNA FRS2 and FRS3 cells was not significantly different in these benign epithelial cell lines." (PMID 22078327, 2011). "Silencing FRS2 and FRS3 had a profound effect on FGF induced proliferation, migration and invasion regardless of the FGF ligand used and in two different cancer cell lines." (PMID 22078327, 2011).
tumor (2 papers, 2011 to 2015). "Nevertheless, they do suggest the potential for using FRS2 and FRS3 as a target to achieve selective enhancing of radio-toxicity in tumours with relative sparing of benign tissue." (PMID 22078327, 2011). "The MSKCC Prostate Oncogenome Project was interrogated for FRS2 and FRS3 transcript expression (n = 131 primary tumours with mRNA data available) using the cBio Cancer Genomics Portal." (PMID 22078327, 2011). "FRS2 and FRS3 are not over-expressed in tumours but targeted dual inhibition may selectively adversely affect malignant but not benign prostate cells." (PMID 22078327, 2011). "Only 6% and 8% of tumours had any changes in FRS2 and FRS3 expression compared to normal controls respectively." (PMID 22078327, 2011).
FRS3 also shares sentences with these, for which no sentence is quoted: breast carcinoma (2 papers); blood cancer (1); breast tumours (1); fibrosis (1); hepatocellular carcinoma (1); lung carcinoma (1); melanoma (1).